USP9X (ubiquitin specific peptidase 9 X-linked)
Diseases named in the same sentence as USP9X in open-access papers (continued):
Sharing a sentence is not in itself a finding about the gene and the disease.
melanoma (continued). "Both Usp9x and Ets-1 KD consistently and effectively suspended 3D growth of NRAS mutant melanoma derived from metastatic lesions." (PMID 28198367, 2017). "To further elucidate the role of Usp9x in melanoma and examine the sensitivity of NRAS mutant tumours to Usp9x KD and inhibition, we first assessed the effects of Usp9x KD on specific RAS proteins in highly metastatic NRAS and BRAF mutant melanomas." (PMID 28198367, 2017). "In two melanoma cell lines (SK-Mel29, WM1366), Usp9x activated NRAS promoter activity by ∼2-fold, while Ets-1 expression increased promoter activity by >2.5-fold." (PMID 28198367, 2017). "We hypothesized that if Usp9x and SOX2 play an essential role in melanoma cell growth, SOX2 and Usp9x should be co-overexpressed in melanoma." (PMID 33613844, 2021). "USP9X was shown to interact directly with ETS-1 and prevent its proteasomal degradation through deubiquitination, promoting ETS-1 transcriptional activity at the NRAS promoter in melanoma cells." (PMID 34066106, 2021). "Usp9x knockdown, as well as inhibition with DUB inhibitor, G9, blocked SOX2 expression, suppressed in vitro colony growth, and induced apoptosis of BRAF-mutant melanoma cells." (PMID 33613844, 2021). "Usp9x is a deubiquitinating enzyme with altered expression in melanoma; however its functional contribution in this context is not clear." (PMID 28198367, 2017). "There was co-incident and significant overexpression of Usp9x, Ets-1 and NRAS in melanoma versus nevi, but Usp9x expression was not notably different between primary and metastatic melanoma." (PMID 28198367, 2017). "In melanoma, both MEK and BRAF inhibition led to an induction of Ets-1 and NRAS expression that could be blocked by Usp9x inhibition." (PMID 28198367, 2017). "We further demonstrated that SOX2 and Usp9x proteins were moderately upregulated in metastatic melanoma patients, and we hypothesized that SOX2 stabilization by Usp9x drives protein expression necessary for melanoma growth, survival and invasion." (PMID 33613844, 2021). "Notably, Ets-1 is induced by BRAF or MEK kinase inhibition, resulting in increased NRAS expression, which could be blocked by inactivation of Usp9x and therapeutic combination of Usp9x and MEK inhibitor fully suppressed melanoma growth." (PMID 28198367, 2017). "However, in melanoma SOX2 regulation by Usp9x has not been previously reported." (PMID 33613844, 2021). "Usp9x KD but not Usp34 KD reduced SOX2 levels in both BRAF mutant A375, SK-Mel28, and NRAS-mutant SK-Mel147 melanoma cell lines." (PMID 33613844, 2021). "USP9X effects on ETS-1 stability appear not to extend to ETS-2, because USP9X knockdown in melanoma cells decreased ETS-1 protein levels but left ETS-2 unaffected." (PMID 34066106, 2021). "Usp9x KD reduced the stability of Ets-1 in both BRAF and NRAS mutant melanoma and decreased NRAS, but not total RAS protein levels." (PMID 28198367, 2017).
B-cell lymphoma (8 papers, 2016 to 2025). "In diffuse large B cell lymphoma (DLBCL) and follicular lymphoma (FL), USP9X deubiquitinates Mcl-1 and protects it from degrading, while high-level Mcl-1 is associated with malignant B-cell proliferation and poor outcomes in B-cell lymphoma patients." (PMID 34454635, 2021). "Accordingly, aggressive B‐cell lymphoma lines with USP9X and associated XIAP overexpression exhibit increased chemoresistance, reversed by specific inhibition of either USP9X or XIAP." (PMID 27317434, 2016). "Knockdown of USP9X leads to suppressed lymphoma growth and increased sensitivity to chemotherapy by destabilizing X-linked inhibitor of apoptosis protein (XIAP) in B-cell lymphoma, independently of Mcl-1." (PMID 34454635, 2021). "USP9X was found to be highly expressed in samples obtained from patients with aggressive B-cell lymphoma." (PMID 34454635, 2021). "Recent studies have demonstrated that USP9X deubiquitinates the X-linked inhibitor of apoptotic protein (XIAP) to promote mitotic survival in aggressive B-cell lymphomas through RNAi-mediated knockdown of USP9X." (PMID 32354135, 2020). "We find that primary human aggressive B‐cell lymphoma samples exhibit high USP9X expression that correlate with XIAP overexpression." (PMID 27317434, 2016). "Indeed, human aggressive B-cell lymphoma displays high USP9X-XIAP expression levels, which increase chemoresistance." (PMID 31795161, 2019). "Finally, aggressive B cell lymphoma cell lines with USP9X and XIAP overexpression exhibit increased chemoresistance, reversed by specific inhibition of either USP9X or XIAP." (PMID 27766120, 2016). "Hence, USP9X is a potential prognostic and therapeutic target in aggressive B-cell lymphoma." (PMID 31795161, 2019). "Furthermore, primary human aggressive B cell lymphomas exhibit high USP9X expression, which correlates with XIAP overexpression and high USP9X/XIAP expression is associated with shorter event-free survival in patients treated with spindle poison-containing chemotherapy." (PMID 27766120, 2016). "USP9X also can induce deubiquitylation and stabilization of XIAP, resulting in increased resistance toward MTAs in aggressive B‐cell lymphoma." (PMID 36967563, 2023). "Knockdown of USP9X results in downregulation of MCL1, which enhances cell apoptosis in human follicular lymphomas and B-cell lymphomas." (PMID 32354135, 2020). "Overexpression of USP9X and XIAP is identified as a predictive biomarker for chemotherapy resistance in aggressive B‐cell lymphoma." (PMID 27317434, 2016). "USP9X has previously been reported to deubiquitinate and consequently stabilize the prosurvival BCL2 family member MCL1 by preventing its proteasomal degradation, thereby promoting cell survival and contributing to chemoresistance in B-cell lymphoma." (PMID 31795161, 2019). "Therefore, USP9X and XIAP are potential predictive biomarkers and targets in combined therapeutical approaches in aggressive B cell lymphoma." (PMID 27766120, 2016). "Together, we specify the USP9X–XIAP axis as a regulator of the mitotic cell fate decision and propose that USP9X and XIAP are potential prognostic biomarkers and therapeutic targets in aggressive B‐cell lymphoma." (PMID 27317434, 2016).
leukemia (8 papers, 2014 to 2025). A malignant (clonal) hematologic disorder, involving hematopoietic stem cells and characterized by the presence of primitive or atypical myeloid or lymphoid cells in the bone marrow and the blood. "Inhibition of USP9X by its inhibitor WP1130 or G9 shows potent anti-leukemia effects in FLT3-ITD-driven cells by blocking downstream signaling events of FLT3." (PMID 34454635, 2021). "USP9X inhibition reduces leukemia cell growth via repressing mTORC1 activity, enhances spontaneous apoptosis and overcomes glucocorticoid resistance in B-ALL." (PMID 34454635, 2021). "U2AF1 p.R35L was shown to induce aberrant splicing of downstream target genes, and shRNA knockdown of MED12 and USP9X was shown to confer resistance to apoptosis following T-ALL relevant chemotherapy drug treatment in Jurkat leukemia cells." (PMID 27602765, 2016). "In addition, we demonstrated that the depletion of ZBTB38, or its regulator deubiquitinase USP9X, enhances the cytotoxicity of 5-azacytidine derivatives in different cancer and leukemia cells, which was concomitant with the enhanced expression of CDKN1C mRNA." (PMID 30310057, 2018). "For instance, the deubiquitinating activity of USP9X regulates proper targeting and association of Survivin and Aurora B proteins to the centromeres, USP39 regulates the mRNA splicing of Aurora B, while USP14 was reported to regulate the stability of Aurora B in leukemia cells." (PMID 34445214, 2021). "Our previous study demonstrated that USP9X inhibition in FLT3-ITD-positive AML induced the K63-Ub processing of receptor-type tyrosine kinases to form aggresomes, suggesting a rapid removal mechanism for the misfolded proteins in leukemia cells." (PMID 39408703, 2024). "The controversial role of USP9X in leukemia has not been fully elucidated yet; some studies classify USP9X as an oncogene, while other studies reported it as an oncosuppressor, suggesting that it displays a context-specific function." (PMID 32674429, 2020).
lymphoma (8 papers, 2012 to 2019). A malignant (clonal) proliferation of B- lymphocytes or T- lymphocytes which involves the lymph nodes, bone marrow and/or extranodal sites. "Immunohistochemical staining of follicular lymphomas and normal lymphoid tissue samples have shown that USP9X levels are increased in the lymphomas." (PMID 27783990, 2016). "Mcl-1 ubiquitination is thus offset by the activities of USP9X and it has been reported that increased USP9X expression correlates with increased Mcl-1 protein levels and a poor prognosis in lymphoma patients." (PMID 23171055, 2012). "USP9X has been shown to interact with β-catenin both in vivo and in vitro in mouse lymphoma cells." (PMID 27783990, 2016). "Possible roles of USP9x-mediated regulation of AMOT in lymphoma remain to be explored." (PMID 27462448, 2016). "It is therefore tempting to speculate that changes in USP9x activity might have a more significant effect on ITCH activity in lymphoma." (PMID 27462448, 2016). "WP1130 (WP) is a small molecule inhibitor of multiple DUBs (USP9X, 5, 14, UCHL5) that increases cl-PARP and poly-Ub accumulation in lymphoma cells and decreases the oncogenic transcription factor ERG, a key driver of PCa27,48." (PMID 30177856, 2018). "Moreover, knockdown of USP9X or XIAP significantly delays lymphoma development and increases sensitivity to spindle poisons in a murine Eμ‐Myc lymphoma model." (PMID 27317434, 2016).
pancreatic cancer (8 papers, 2013 to 2022). "In pancreatic cancer patients, low USP9X levels were associated with metastatic burden in advanced disease and with poor survival." (PMID 29156578, 2017). "Studies related to other malignancies, such as pancreatic cancer, demonstrated that Usp9X is necessary to drive tumor growth by inhibition of cell death." (PMID 30478285, 2018). "Evidence was provided that USP9X protein levels are low in most of pancreatic cancer cell lines: following treatment of the cells with chromatin modulating agents, USP9X levels are significantly increased." (PMID 29156578, 2017). "Suppression of Usp9X levels reduced the growth of several different pancreatic cancer cell lines, including BxPC3 and others, and consistent with that observation altered the cell cycle profile of these cells." (PMID 26872380, 2016). "One study demonstrated that knockdown of USP9X in the human pancreatic tumor cell line, BxPC-3, reduces xenograph tumor growth, especially when combined with the BH3 mimetic ABT-737." (PMID 23667531, 2013). "Finally, in disease animal models, conditional deletion of USP9X cooperates with oncogenic KRAS to induce pancreatic cancer development." (PMID 29156578, 2017). "The protein expression of WT1 was measured in pancreatic cancer cells, which were transduced with specific shRNAs for USP5, USP9x or USP14, respectively." (PMID 31845546, 2020). "We demonstrate that the expression of the deubiquitinase USP9X, which activates ITCH stability, is increased in 9F7-F11-treated pancreatic cancer cells." (PMID 27203743, 2016). "Our findings are in line with previous observations in pancreatic cancer, in which cell death by another BH3-mimetic was enhanced by blocking the binding of Usp9X to Mcl-1 in vitro and in vivo." (PMID 26872380, 2016). "However, USP9X may play multiple roles in pancreatic cancer." (PMID 23667531, 2013). "Similarly to the knock-down of Usp9X, the deubiquitinase inhibitor WP1130 exerted anti-proliferative effects on pancreatic cancer cells." (PMID 26872380, 2016).
pancreatic ductal adenocarcinoma (8 papers, 2013 to 2017). An infiltrating adenocarcinoma that arises from the epithelial cells of the pancreas. "However, another observation found that low USP9X protein and messenger RNA expression in pancreatic ductal adenocarcinoma (PDA) were inversely associated with poor survival after surgery." (PMID 24152793, 2013). "Conversely, USP9X has tumor suppressor functions in certain kinds of cancer, such as pancreatic ductal adenocarcinoma (PDA)." (PMID 27517496, 2016). "On the other hand, decreased USP9X mRNA was founded to correlate with poor prognosis in pancreatic ductal adenocarcinoma." (PMID 27517496, 2016). "Conversely, in pancreatic ductal adenocarcinoma, decrease in USP9X mRNA correlated with poor prognostic outcomes." (PMID 25672900, 2015).
X-linked intellectual disability (7 papers, 2013 to 2025). An X-linked intellectual deficiency in which not enough information is known, reported or published to indicate whether a gene causes non-syndromic or syndromic presentations. "Dysregulation of USP9X has been linked to cancers and X-linked intellectual disability, as well as in CNS developmental disorders." (PMID 39974971, 2025). "We also found a likely pathogenic variant in USP9X (encoding ubiquitin specific peptidase 9 X-linked) that is involved in X-linked intellectual disability, which was inherited from her mother who had dyscalculia and dyspraxia." (PMID 35227307, 2022). "USP9X encodes an enzyme that plays a key role in human neural development and the p.Y1268C mutation has been shown to be involved in X-linked intellectual disability." (PMID 35227307, 2022). "Initial studies reported three male individuals with non-syndromic X-linked intellectual disability, all carrying missense variants in USP9X." (PMID 33335288, 2021). "USP9X is a candidate gene for human neurodevelopmental disorders, including lissencephaly, epilepsy and X-linked intellectual disability." (PMID 23861879, 2013). "Furthermore, we found a likely pathogenic missense variant in USP9X (NM_001039590.2: c.3803A > G/p.Y1268C) involved in X-linked intellectual disability, which was inherited from her mother who had academic difficulties, related to dyscalculia and dyspraxia." (PMID 35227307, 2022). "In addition to its roles in mitosis and carcinogenesis, USP9X is known to be required for neural development, and USP9X deficiency is associated with X-linked intellectual disability in patients." (PMID 31671755, 2019). "USP9X variants have been reported in patients with X-linked intellectual disability." (PMID 31666975, 2019). "While it is true that the partial specificity of WP11330 could confound the obtained results, interestingly, USP9X has been earlier reported to be involved in X-linked intellectual disability." (PMID 31130875, 2019). "USP9X is linked to lissencephaly, via its interaction with DCX, and USP9X is a candidate gene in X-linked intellectual disability and epilepsy." (PMID 23861879, 2013).
autism (6 papers, 2015 to 2025). Persistent deficits in social interaction and communication and interaction as well as a markedly restricted repertoire of activity and interest as well as repetitive patterns of behavior. "One synonymous variant and multiple pathogenic missense variants in USP9X are identified with autism, and ASD." (PMID 39519104, 2024). "Males with pathogenic USP9X variants have severe disease with global developmental delay, brain malformations most commonly involving the ventricles, cerebellum, and corpus callosum, hypotonia, seizures, autism, growth failure, myopia, genitourinary malformations, and scoliosis." (PMID 36653407, 2023).
diffuse large B-cell lymphoma (6 papers, 2016 to 2024). "Based on a recent experiment, USP9X overexpression was found associated with diffuse large B-cell lymphoma (DLBCL) development and progression." (PMID 39664521, 2024). "USP9X expression correlated with MCL-1 overexpression and/or poor outcome in follicular lymphoma, diffuse large B-cell lymphoma (DLBCL) and multiple myeloma (MM)." (PMID 33308268, 2020). "One report has presented evidence that USP9x can promote tumor cell survival through stabilization of the pro-survival BCL2 family member MCL1 in human follicular lymphomas and diffuse large B-cell lymphoma and multiple myleomas." (PMID 27462448, 2016). "We show that upregulation of USP9X and consequently of XIAP promote mitotic survival and increased resistance to mitotic spindle poisons in diffuse large B‐cell lymphoma." (PMID 27317434, 2016).
epilepsy (6 papers, 2013 to 2022). A brain disorder characterized by episodes of abnormally increased neuronal discharge resulting in transient episodes of sensory or motor neurological dysfunction, or psychic dysfunction. "For the combined African American and European American cohorts, we found a statistical association (p = 0.0350) between USP9X rare coding variants and epilepsy." (PMID 25763846, 2015). "In humans USP9X has been implicated in lissencephaly and epilepsy and is an X-linked Intellectual Disability candidate gene." (PMID 23861879, 2013). "Interestingly, however, in the fruit fly Drosophila, loss-of-function mutations in the ortholog of USP9X, faf, were shown to confer resistance to seizures when crossed with the prickle model of epilepsy, pksple/+." (PMID 35327449, 2022). "Here, we showed that human USP9X mutations are associated with epilepsy." (PMID 25763846, 2015). "In contrast to this suggestion, in humans, USP9X has been postulated to be an epilepsy candidate gene." (PMID 25763846, 2015). "In addition, mutations in Doublecortin that specifically disrupt its ability to interaction with USP9X, result in lissencephaly and severe epilepsy, further highlighting the importance of USP9X function for normal brain development." (PMID 28341829, 2017). "This further supports the assertion that USP9X may be a novel epilepsy gene." (PMID 25763846, 2015). "For example, it is known that USP9X utilises alternative 3′UTR sequences in response to neuronal activity, and this might provide a specific miRNA-based therapeutic target for treatment in neurological disorders such as epilepsy." (PMID 25672900, 2015).
follicular lymphoma (6 papers, 2013 to 2023). Follicular lymphoma is a form of non-Hodgkin lymphoma characterized by a proliferation of B cells whose nodular structure of follicular architecture is preserved. "Recent studies have shown that the overexpression of USP9X in follicular lymphoma correlates with increases in levels of the anti-apoptotic protein MCL1 and poorer prognosis." (PMID 23667531, 2013).